LGALS3 (galectin 3)
Diseases named in the same sentence as LGALS3 in open-access papers (continued):
Sharing a sentence is not in itself a finding about the gene and the disease.
prostate carcinoma (84 papers, 2006 to 2026). A carcinoma that arises from epithelial cells of the prostate gland. "In mouse models of breast and prostate cancers, galectin-3 was cleaved by MMP2 and MMP9 and this was associated with enhanced tumor growth and angiogenesis." (PMID 36873388, 2023). "Silencing of galectin-3 expression by methylation of its promoter was associated with early stages of prostate cancer." (PMID 36861129, 2023). "Emerging studies are associating the expression of the Galectin-3 with the immune response against prostate cancer, as well as to the success of effective immunotherapy." (PMID 36936148, 2023). "For example, the change Pro64 for His64 has been associated with alterations in galectin-3 function and with breast and prostate cancer incidence." (PMID 27242966, 2016). "Galectin-3 knockdown in prostate cancer cells by small interfering RNA was associated with reduced cell migration, invasion, cell proliferation, anchorage-independent colony formation, and tumor growth in nude mice." (PMID 23658855, 2010). "Since no alternative test is available to replace it, we have initiated a trial with the purpose of establishing whether Galectin-3 (Gal-3) serum level and/or the patients immune response to PSA and Gal-3 antigens could complement the PSA test as diagnostic tools for prostate cancer patients." (PMID 27741522, 2017). "Although larger-scale validation studies involving more patients are still needed, vinculin and galectin-3 seem to be promising urinary biomarker candidates for recurrent prostate cancer, while secernin-1 seems to be a useful tissue diagnostic biomarker candidate for prostate cancer." (PMID 25667921, 2015). "The preliminary in vitro and in vivo results in a PC3 cell line and tumor model indicate that the tumor specificality of the therapeutic agent(s) can be increased by targeting galectin-1 and galectin-3, known for their overexpression in prostate cancer." (PMID 37445799, 2023). "Further investigation is important to elucidate the relationship between the expression of the Galectin-3 and its regulation, cleavage and function in different stages of prostate cancer and CRPC." (PMID 36936148, 2023). "This review provides an overview of the current and emerging knowledge on Galectin-3 in cancer biology with focus on prostate cancer and the interplay with estrogen receptor (ER) signaling pathways, present in androgen-independent prostate cancer cells." (PMID 36936148, 2023). "Our laboratory and other groups have shown the expression of the Galectin-3 in androgen-independent prostate cancer cells PC-3 (derived from bone metastasis) and DU-145 (derived from brain metastasis), used in vitro and in xenograft implants, as a CRPC models." (PMID 36936148, 2023). "Further understanding of the role of Galectin-3 and ER in prostate cancer will enhance our understanding of the molecular mechanisms of prostate cancer development and the future treatment of this disease." (PMID 36936148, 2023). "N-acetyl-d-lactosamine is a Galectin-3 inhibitor that plays a role in immunosuppression mediated by Gal-3 and prostate cancer stem cell-like cells." (PMID 37649476, 2023). "TFD10 is a glycopeptide isolated from polar cod fish that displayed inhibitory effects in prostate cancer metastasis by blocking galectin-3-mediated angiogenesis and tumor cell-endothelial cell interactions and inhibiting the apoptosis of activated T cells." (PMID 36873388, 2023). "Among the targets, galectin-3 (Gal-3) is of particular interest for developing prostate cancer-specific agents." (PMID 37445799, 2023). "The studies in prostate cancer have mainly focused on Galectin-1 and Galectin-3, but the importance of Galectin-4, Galectin-7, Galectin-8, and Galectin-9 has also been highlighted (reviewed by 11, 33, 34)." (PMID 36936148, 2023). "In primary prostate cancer and metastatic disease, the expression of the Galectin-3 decreased compared to normal and premalignant tissue." (PMID 36936148, 2023).
prostate carcinoma (continued). "It has been reported that MCP inhibits myeloma/prostate cancer/bladder tumor /gastrointestinal cancer via interaction with galectin-3." (PMID 36432183, 2022). "Mac-2binding protein (Mac-2BP) plays a role in cell–cell and cell–matrix adhesion by binding to Galectin-1, Galectin-3, fibronectin and collagen, which is a candidate biomarker in nonalcoholic fatty liver disease diagnosis and prostate cancer diagnosis." (PMID 36010914, 2022). "In prostate cancer, low doses of docetaxel downregulate tumor galectin-3, even in docetaxel-resistant patients." (PMID 34572756, 2021). "P-MCP is an oral competitive inhibitor of galectin-3, and preliminary preclinical and clinical data suggest that it is active in patients with prostate cancer." (PMID 34959847, 2021). "As a result of the said tumor galectin-3 inhibition, vaccination induces long-term anti-prostate cancer immune protection." (PMID 34572756, 2021). "Galectin-3 plays an important role in tumor progression and metastasis in different types of tumors, such as lung cancer and prostate cancer." (PMID 32190664, 2020). "The intense expression of galectin-3 has also been observed in lung, breast, colorectal, and prostate carcinomas." (PMID 32190664, 2020). "Phosphorylation of tyrosine 107 can give the cleavage of galectin-3, and the ratio of phosphorylated/dephosphorylated galectin-3 can be used for the prognosis of prostate cancer as well as be a target for potential treatment." (PMID 29950926, 2018). "Galectin-3 inhibition contributes to calpain activation and sensitizes prostate cancer cells to cisplatin." (PMID 28546799, 2017). "As another cancer maker, the interest in Galectin-3 (Gal-3) stems from the evidence that it is a pro-inflammatory sugar-binding protein involved in prostate cancer malignancy, and is considered to be a promising therapeutic target." (PMID 27741522, 2017). "The 2D-DIGE experiments revealed galectin-3 as another potential new biomarker candidate for recurrent prostate cancer." (PMID 25667921, 2015). "Our previous report indicated that patients with metastases arising from prostate cancer have a higher serum galectin-3 concentration." (PMID 26158764, 2015). "Nevertheless, nuclear galectin-3 was discovered to promote apoptosis in human prostate cancer cells." (PMID 25730388, 2015). "Galectin-3 promotes chemoresistance in prostate cancer, cholangiocarcinoma, and thyroid carcinoma, while its inhibition sensitizes prostate cancer cells to cisplatin treatment." (PMID 25669973, 2015). "Galectin-3 was verified as a potential prognostic biomarker candidate by analyzing prostate cancer patient urine samples with MRM-MS." (PMID 25667921, 2015). "Galectin-3 is similar to PAP which is already discussed as a potential biomarker candidate for recurrent prostate cancer in the literature." (PMID 25667921, 2015). "Earlier we had reported an increased cleavage of galectin-3 in progressive stages of prostate cancer." (PMID 23625538, 2013). "The altered downregulation pattern of galectin-3 observed between tumor stages suggests different roles for galectin-3 in the progression of prostate cancer." (PMID 23663294, 2013). "For example, GSTP1, RASSF1A, RAR2 and LGALS3 promoters are frequently methylated in prostate cancer; while ARF, APC, and DAPK have been found methylated in bladder cancer." (PMID 25419445, 2012). "In contrast, for some tumours such as breast, ovarian and prostate cancer the expression of galectin-3 is inversely correlated with metastatic potential." (PMID 22024187, 2011).
prostate carcinoma (continued). "In the prostate cancer cell line LNCaP that lacks galectin-3 (due to promoter hypermethylation), induced expression of galectin-3 leads to reduced drug-induced apoptosis." (PMID 22039439, 2011). "A recent study describes the use of siRNA and GSC-100/MCP (modified pectin citrate) to inhibit galectin-3 in prostate cancer cell of PC3 and enhance cisplatin treatment response." (PMID 22039439, 2011). "Using tissue array of human breast and prostate cancers it has been showed that galectin-3 is cleaved during cancer progression." (PMID 23658855, 2010). "The expression of galectin-3 was also examined in 145 prostate carcinoma samples using immunohistochemistry." (PMID 23658855, 2010). "A report recently published by our group revealed the role of galectin-3 in progression of prostate cancer." (PMID 23658855, 2010). "Immunohistochemical analysis of a prostate tissue array using differential galectin-3 staining demonstrated an increased cleavage of galectin-3 during the progression of prostate cancer." (PMID 23658855, 2010). "In prostate cancer progression, galectin-3 is mainly studied; and different reports show a down-regulation of this gene." (PMID 19936097, 2007). "We suggest a molecular mechanism where ER, Galectin-3 and β-catenin can modulate nuclear transcriptional events, such as, proliferation, migration, invasion, and anchorage-independent growth of androgen-independent prostate cancer cells." (PMID 36936148, 2023). "Other studies showed a decrease in the expression of the Galectin-3 in breast, ovary, prostate cancers, advanced uterine adenocarcinoma, basal cell of the skin, epithelial skin, and malignant salivary gland neoplasms, compared to the corresponding normal tissue (reviewed by 23, 26)." (PMID 36936148, 2023). "We identify an unexpected function of PODXL as a decoy receptor that relieves the invasion-inhibiting effect of the glycocalyx component galectin-3 (GAL3) and demonstrate that the levels of this switch identify prostate cancer patients with high metastasis and poor outcome." (PMID 36735782, 2023). "Furthermore, prostate specific membrane antigen and galectin-3 expression are good indicators of tumor aggressiveness, and their combined expression can be valuable tool for prostate cancer diagnosis and treatment in future." (PMID 35681683, 2022). "Furthermore, galectin-3 downregulation is a pre-requisite for optimal lymphocyte activation when a dendritic cell-based vaccine is used in prostate cancer." (PMID 34572756, 2021). "Indeed, we recently demonstrated that preconditioning the tumor microenvironment through galectin-3 downmodulation is a pre-requirement for a long-term protective vaccine strategy in prostate cancer." (PMID 34572756, 2021). "Consequently, inhibition of galectin-3 in tumor cells leads to an optimal anti-prostate cancer vaccination." (PMID 34572756, 2021). "Elevated galectin-3 serum level was reported in prostate cancer patients." (PMID 34959847, 2021). "Here we show increased binding of Galectin-3 in prostate cancer cells treated with androgens." (PMID 27428423, 2016). "Galectin-3 (Gal-3), an oncogenic pro-inflammatory protein, has been suggested as a possible complementary diagnostic candidate to prostate specific antigen (PSA) blood test for prostate cancer patients." (PMID 27741512, 2016). "In this context, a specific peptide targeting galectin-3 was able to inhibit prostate cancer cell migration, raising the possibility that galectin-3 inhibitors might avoid tumor spread." (PMID 27242966, 2016). "Thus, galectin-3 levels in urine are a promising biomarker candidate for the prediction of prostate cancer progression." (PMID 25667921, 2015). "In our study, we analyzed galectin-3 levels in urine of prostate cancer patients using MRM." (PMID 25667921, 2015).
prostate carcinoma (continued). "In addition, we also found differential expression levels of PAP and galectin-3, proteins which have already been discussed in literature as potential biomarker candidates for recurrent prostate cancer." (PMID 25667921, 2015). "Intracellular galectin-3 is most known as an identifier for both thyroid and prostate cancer." (PMID 25730388, 2015). "Although the fate of CLICs has not been tracked, Erbb3 may be transported to the nucleus of prostate cancer cells through such a mechanism and we speculate that Galectin-3 and select cargo/client proteins may make this journey together." (PMID 25869099, 2015). "Interestingly, galectin-3 is downregulated in the serum of prostate cancer patients compared to serum of healthy controls." (PMID 25667921, 2015). "Galectin-3 may be cleaved by proteases during prostate cancer progression, and PC3 prostate cancer cell line with reduced galectin-3 showed reduced tumor growth in xenografts." (PMID 22039439, 2011). "Prostate cancer tissues had both galectin-3 and Beclin1 levels above normal tissue levels." (PMID 22039439, 2011). "Similarly, over-expression of galectin-3 in the prostate cancer cell line LNCaP that lacks galectin-3 expression led to inhibition of tumor growth." (PMID 22039439, 2011). "High levels of galectin-3 in the prostate cancer samples could indicate, low stage and less progressive disease." (PMID 22039439, 2011). "In the cancers with elevated galectin-3 and Beclin1 (liver and prostate cancers), targeting both may be of benefit." (PMID 22039439, 2011). "In prostate cancer and cell line LNCaP, promoter methylation status affected tissue expression of galectin-3; hence proteomics may need correlation with methylation status." (PMID 22039439, 2011). "High galectin-3 levels in prostate cancers in this study may support the findings in model animal studies." (PMID 22039439, 2011). "The data implicate galectin-3 in prostate cancer progression and suggest that galectin-3 may serve as both a diagnostic marker and therapeutic target for future disease treatments." (PMID 23658855, 2010). "The authors suggest that the methylation of galectin-3 promoter may constitute a powerful tool for early diagnosis of prostate cancer." (PMID 23658855, 2010). "Furthermore, very recently, it has been shown for the first time in prostate cancer cell lines that silencing of galectin-3 expression is regulated by promoter hypermethylation." (PMID 19936097, 2007). "Furthermore, Galectin-3 can inhibit apoptosis in prostate cancer cells." (PMID 36936148, 2023). "In the hormone-sensitive prostate cancer tissue when compared to the respective benign tissue either localized far distant from the malignant lesion or directly neighboring the primary tumor, the expression of the Galectin-3 was significantly decreased in the prostate cancer tissue." (PMID 36936148, 2023). "In addition, low doses of docetaxel inhibited the expression of the Galectin-3 in prostate cancer cells as well as in clinical samples of patients with metastatic cancer and CRPC, controlling tumor recurrence by increasing proliferation and infiltration of CD8+ cytotoxic T." (PMID 36936148, 2023). "Nakajima and colleagues had described a galectin-3-dependent activation of Notch1 signaling in a system that models tumor cell/osteoblast and osteoclast interactions, critical events in the maintenance of bone metastasis found in different cancers, such as breast and prostate cancers." (PMID 27242966, 2016). "However, in later stages of prostate cancer, expression and formation of Mgat5/galectin-3 lattices may stimulate and elevate the expression of CAV1 through phosphorylation, resulting in up-regulated CAV1 expression in advanced prostate tumours." (PMID 26112043, 2015).
prostate carcinoma (continued). "Association of LGALS3 (lectin, galactoside-binding soluble 3) is reported with endometrial, breast and colorectal cancer, and CDKN3 (cyclin-dependent kinase inhibitor 3) is known to be involved in hepatocarcinogenesis and breast and prostate cancer development." (PMID 21708004, 2011). "On the other hand, recent study using biopsy samples, representing different stages of the primary prostate cancer, showed that prostate specific membrane antigen (PSMA), Galectin-1 and Galectin-3 are the most abundantly expressed glycoproteins." (PMID 36936148, 2023). "In early stages of prostate cancer, the expression of CAV1 is lost and the expression of Mgat5 and galectin-3 is at low levels." (PMID 26112043, 2015). "Antibodies that recognize galectin-3 and RGD motif peptides reduce the ability of prostate cancer cells to bind to endothelial tissue." (PMID 16859559, 2006). "In addition, the expression of the Galectin-3 was also investigated in normal, BPH, and various stages of the prostate cancer which showed decreasing immunopositivity during stage evolution." (PMID 36936148, 2023). "Our laboratory recently demonstrated that tumor galectin-3 is a potent negative checkpoint that suppresses lymphocyte proliferation in a prostate cancer microenvironment." (PMID 34572756, 2021). "For example, modified citrus pectin (MCP), which is a non-toxic polysaccharide galectin-3 antagonist, augments prostate cancer cells to cisplatin." (PMID 30267152, 2018). "In contrast, galectin-3 is not expressed or its expression is decreased in prostatic cancer cells and it is only present in the cytoplasm." (PMID 25667921, 2015). "Consistent with our 2D-DIGE results and other published data, we were able to detect galectin-3 downregulation in the urine of prostate cancer patients with recurrence compared to patients without recurrence." (PMID 25667921, 2015). "Abl kinases also play a role in motility/invasion of prostate cancer cells, as c-Abl/Arg–mediated phosphorylation of galectin-3 prevented its cleavage by PSA thereby increasing full-length extracellular galectin-3 and promoting migration and invasion of PCa cells." (PMID 24223753, 2013). "However, two or multiple genes cohort such as GSTP1/LGALS3 or GSTP1/RARβ2/APC has been shown to be more specific and sensitive biomarkers for prostate cancer." (PMID 25419445, 2012). "In prostatic cancer cells, galectin-3 was usually not expressed or decreased compared with the normal glands." (PMID 23658855, 2010). "Functional studies using prostate cancer cell lines suggest that the expression of the Galectin-3 is not regulated by AR, but other hormones and their receptors, such as ER, could be involved in the regulation of the expression of the Galectin-3." (PMID 36936148, 2023). "They found that most of the non-tumoral tissue exhibited moderate immunostaining for Galectin-3 localized in both nucleus and cytoplasm and prostate cancer cells showed decrease of the expression of the Galectin-3 or not expression compared to the normal tissue." (PMID 36936148, 2023). "However, LNCaP prostate cancer cells (a non-expressing galectin-3 cell line) treatment with pectins showed some apoptotic effects which were due to mechanisms not mediated by galectin-3 inhibition." (PMID 29185464, 2017). "Galectin-3 and MCP have different effects on apoptosis: galectin-3 has a BH1 domain of BCL2 that can protect cells from apoptosis and transfection with the lectin makes T-cells resistant to this type of cell death; MCP, in contrast, promotes apoptosis in angiosarcoma and prostate cancer cell lines." (PMID 21494626, 2011). "Our previous work identified LGALS3, KLF4, and non-canonical WNTs (i.e., WNT5A), as genes enriched in CTCs from overtly metastatic pancreatic, breast, and prostate cancer mouse models and patients." (PMID 32620742, 2020).